ENSG00000255432 (novel protein)
Gene: Protein-coding gene on chromosome 11 (62,649,694 to 62,665,178, reverse strand). Ensembl gene ENSG00000255432.
Genetic constraint (gnomAD): Loss-of-function variants: 6 observed, 9.83 expected, observed/expected ratio (o/e) 0.61, 90% interval 0.33 to 1.2. That is too few expected variants to judge how well the gene tolerates losing a copy. Missense variants: 117 observed, 116.48 expected, observed/expected ratio (o/e) 1, 90% interval 0.86 to 1.17. Synonymous variants: 50 observed, 45.13 expected, observed/expected ratio (o/e) 1.11, 90% interval 0.88 to 1.4.